BMI1 (BMI1 proto-oncogene, polycomb ring finger)
Diseases named in the same sentence as BMI1 in open-access papers (continued):
Sharing a sentence is not in itself a finding about the gene and the disease.
breast carcinoma (continued). "To date, the proto-oncogene Bmi-1 has been reported to be up-regulated in a large number of neoplasias, namely in lymphomas, cerebral tumours, breast cancer and other epithelial tumours and to be an oncogene associated with poor prognosis in various tumours." (PMID 20377880, 2010). "Our previous data showed an inverse correlation between BMI1 and Mel-18 expression in cultured human fibroblasts and breast cancer cells." (PMID 20170541, 2010). "AKT was selected in this study because AKT activity is constitutively high in many cancers and a recent study has suggested that Bmi1 regulates AKT activity in breast cancer cells." (PMID 19917110, 2009). "Here, we report on a study regarding the RNAi-mediated silencing of the Bmi-1 gene in breast cancer." (PMID 21637439, 2009). "Down-regulation of Bmi-1 inhibited the proliferation and increased the chemosensitivity of MCF-7 cells, indicating that Bmi-1 can be developed into a therapeutic option for the treatment of breast cancer." (PMID 21637439, 2009). "A study on Bmi-1 mRNA levels in several breast cancer cell lines (MCF-7, MDA-MB-468, MDA-MB-231, T47D) was carried out." (PMID 21637439, 2009). "In the literature, the BMI1 gene is reported to be related to the clinicopathologic features and prognosis in other human cancers, including breast cancer, colon cancer, and lung cancer." (PMID 19228380, 2009). "We further show that high BMI1 expression is limited to the luminal breast cancer subtypes, and is inversely correlated with PcG members from the silencing initiation complex, PRC2." (PMID 19099573, 2008). "These cells are thought to be more resistant to therapy and a BMI1 overexpression signature has subsequently been correlated with poor prognosis in several tumour types, including breast cancer." (PMID 19099573, 2008). "We have analysed the expression of EZH2 and BMI1 in a well-characterised dataset of 295 human breast cancer samples." (PMID 19099573, 2008). "In light of the potential role of PcG proteins in cancer stem cells, we investigated the controversial role of BMI1 in breast cancer and compared it with EZH2 to obtain more of an insight into polycomb function in tumourigenesis." (PMID 19099573, 2008). "Bmi-1 mRNA in plasma detected by real-time PCR was identified in 43.2% of the breast cancer samples and in 55% of the healthy controls." (PMID 17711569, 2007). "Since Polycomb-group genes are overexpressed in breast cancer, BMI1 is a relevant candidate to test in HMEC transformation assays." (PMID 17573968, 2007). "In conclusion, in the present study, we examined the mRNA levels of Bmi-1 in plasma in a large series of primary breast carcinomas." (PMID 17711569, 2007). "Bmi-1 expression levels were quantified in plasma of 111 breast cancer patients and in 20 healthy controls by real-time quantitative polymerase chain reaction." (PMID 17711569, 2007). "Modulation of Bmi-1 is found in several tumor tissues, including primary breast carcinomas; however, analysis of Bmi-1 in plasma of cancer patients has not been reported." (PMID 17711569, 2007). "We evaluated Bmi-1 mRNA in plasma from 111 primary breast carcinomas to investigate the presence at diagnosis of detectable Bmi-1 mRNA in plasma and possible correlations between this event and the specific pathological and clinical parameters of tumors." (PMID 17711569, 2007). "We have created a new model for ERα-positive breast cancer by transduction of normal HMECs with lentiviruses expressing ERα, BMI1, MYC and TERT." (PMID 17573968, 2007). "Bmi-1 mRNA in plasma was identified in 48 of the 111 breast cancer samples (43.2%) and in 11 of the 20 healthy controls (55%)." (PMID 17711569, 2007). "Additionally, we found that breast cancer cells that overexpress MEG8 have decreased the expression levels of some stem cell markers such as BMI1, SOX9 and KLF4 and in some cases also NANOG or SOX2, but not OCT4." (PMID 39706842, 2024).
breast carcinoma (continued). "A similar finding in breast cancer showed that the PcG protein Mel-18 inhibited Bmi-1 and Akt expression, and that constitutively active Akt rescued the tumor-suppressive function of Mel-18 and Bmi-1 inhibition." (PMID 36726797, 2023). "Additionally, BMI1 can promote breast cancer cell proliferation and inhibit autophagy by activating COPZ1 transcription." (PMID 37107648, 2023). "Bmi-1 is also needed for the maintenance and self-renewal of cancer stem-like cells/tumor-initiating cells in leukemia, colorectal cancer, liver cancer, glioma, breast cancer, prostate cancer, head and neck squamous cell carcinoma, and medulloblastoma." (PMID 37219449, 2023). "In breast cancer cells, Bmi-1 expression was also indicative of radioresistance." (PMID 36726797, 2023). "Knockdown of Bmi-1 in breast cancer cells also induced autophagy." (PMID 35897796, 2022). "In breast cancer stem cells (BCSCs), Bmi-1 is a target of the miR-200 family and miR-128 family." (PMID 35897796, 2022). "The results of our previous studies showed that BMI1 silencing caused a reduction in AKT phosphorylation and increased the expression of gene coding for PHLPP1 and PHLPP2 phosphatases in endometrial cancer cells HEC-1A and breast cancer MDA-MD-23 cells." (PMID 36497428, 2022). "BMI1 mediates the Shh pathway-activated mammosphere formation in breast cancer." (PMID 33499351, 2021). "Additionally, recent developments demonstrated the upregulation of BMI1 in human non-small cell lung cancer, breast cancer, colon cancer, human medulloblastomas, and prostate cancer." (PMID 33804165, 2021). "In addition, down-regulation of BMI-1 in breast cancer cells inhibited cellular invasion and proliferation." (PMID 34551814, 2021). "The reduced antitumor immune response implies that high BMI1 expression could promote cancer cell survival in patients with breast cancer, especially those with IDC of the luminal subtype." (PMID 34442383, 2021). "BMI1 is also found overexpressed in breast cancers, and this correlates with MYC expression." (PMID 33804165, 2021). "BetaTrCP promotes the ubiquitination and the degradation of Bmi1 protein in breast cancer cells." (PMID 33014838, 2020). "Hence, BMI1 has been shown to behave as a key regulator in the self-renewal, differentiation and tumour initiation of breast cancer stem cells (BCSC)." (PMID 32524353, 2020). "Interestingly, in breast cancer cell lines, BMI-1 activates the WNT pathway that in turns induces c-MYC activity, therefore maintaining a positive feedback loop between BMI-1 and c-MYC." (PMID 33126754, 2020). "In human breast cancer specimens, Bmi-1 expression was most pronounced in the invasive front of the tumor, but in our study of endometrial carcinoma, diffuse Bmi-1 expression was observed, and no invasive front could be confirmed." (PMID 32059385, 2020). "High expression of BMI1 was associated with longer breast cancer-specific survival (BCSS) independent of other prognostic variables." (PMID 32524353, 2020). "Our results revealed that the simultaneous existence of YB-1 and the other four (SOX2, POU3F2, OCT-4, and OLIG1) or five (SOX2, SALL2, OCT-4, POU3F2, and Bmi-1) transcription factors reverted YB-1-deleted melanoma stem cells or breast cancer stem cells, respectively, into cancer stem cells." (PMID 31375149, 2019). "The high expression of BMI-1 is correlated with poor prognosis so that BMI-1 is considered as a viable therapeutic target in some malignancies, such as colorectal cancer, ovarian cancer, prostate cancer, non-small lung cancer, breast cancer." (PMID 31640758, 2019).
breast carcinoma (continued). "In addition, CAF64-si-SFCM inhibited the stemness properties in breast cancer cells (CD44high/CD24low/ALDHhigh), and downregulated BMI-1 and lin-28B compared to controls." (PMID 29416775, 2018). "Similarly, the PRC1 protein BMI1, whose role is to sustain self-renewal of normal mammary stem cells, also has proto-oncogenic functions in breast cancer." (PMID 30176939, 2018). "The 2 variants, rs1042059 and rs201024480, in BMI‐1 gene belonged to low‐penetrance mutations, and there was no hint of significance with breast cancer risk." (PMID 29691986, 2018). "Knockdown of BMI1 abolished irradiation-induced cell migration in breast cancer cells." (PMID 29100291, 2017). "BMI1 is overexpressed in many cancers, including breast cancer, prostate cancer and GC." (PMID 28415621, 2017). "Silencing BMI1 significantly inhibits tumorogenesis in various cancers including breast cancer." (PMID 28655885, 2017). "The current research shows that irradiation could induce epithelial–mesenchymal transition in breast cancer cells by the upregulation of BMI1." (PMID 29100291, 2017). "We hypothesized that miR-15a/16 could sensitize the breast cancer cells to the chemotherapeutic drug as our results show that miR-15a/16 drastically decreased the BMI1 expression in breast cancer cells." (PMID 28655885, 2017). "Here we emphasized the unique role of miR-15a/miR-16 cluster in their dramatic participation in breast cancer by reducing the oncogene and DNA repair protein BMI1, and therefore inducing impaired repair of damaged DNA via homologous recombination and apoptosis." (PMID 28655885, 2017). "Therefore, we have shown the role of specific miRNAs involved in regulating the expression of BMI1 in response to DNA damage and BMI1 dependent ubiquitination pathway in breast cancer cells." (PMID 28655885, 2017). "Our results indicate that Bmi1 plays a functional role in regulation of CSCs in breast cancer." (PMID 28418883, 2017). "Activation of the Shh pathway induces Bmi1 expression in medulloblastoma and breast cancer." (PMID 29163356, 2017). "Also, interestingly, overexpressed miR-15a, miR-16 not only suppressed BMI1 level but also sensitizes breast cancer to chemotherapeutic drug doxorubicin by triggering intrinsic apoptosis in breast cancer cells." (PMID 28655885, 2017). "Our findings may supply a strategy for targeting the PANDAR/Bmi1/p16INK4A axis as a novel therapeutic application for breast cancer patients." (PMID 26927017, 2016). "We further analyzed the mRNA levels of Bmi1 and E-cadherin in 58 human breast cancer samples." (PMID 26023734, 2015). "To determine the potential role of Bmi-1 in regulation of EMT of breast cancer cells, we determined whether there is a correlation between the expression of Bmi-1 protein with EMT markers in five breast cancer cell lines." (PMID 25734775, 2015). "ERα inhibits the epithelial-mesenchymal transition by suppressing Bmi1 in breast cancer." (PMID 26503703, 2015). "As vimentin elevation and E-cadherin repression are markers of EMT, our results suggested that Bmi-1 might play a role in regulation of EMT of breast cancer cells." (PMID 25734775, 2015). "Furthermore, the knockdown of Bmi-1 completely abolished the ability of the IR to alter, reduce or increase, the migration of breast cancer cells (shBmi-1 vs. NC or WT)." (PMID 25734775, 2015). "Our results indicated that Bmi-1 might be a key gene in regulation of IR-altered breast cancer metastatic potential." (PMID 25734775, 2015). "Furthermore, estrogen stimulation downregulated Bmi1 expression in hormone-dependent breast cancer cells, while in hormone-independent cells, Bmi1 was downregulated by ERα overexpression." (PMID 26023734, 2015). "ERα may modulate the stemness of breast cancer cells by suppressing Bmi1 expression, and may therefore be considered an inhibitor of circulating and migrating cancer stem cells." (PMID 26023734, 2015).
breast carcinoma (continued). "To determine whether Akt mediates IR-induced Bmi-1-regulated migration of breast cancer cells, we analyzed the effect of PI3K inhibitor LY294002 or AKT 1/2 kinase inhibitor AKT I on the migration of the same set of breast cancer cell lines after IR." (PMID 25734775, 2015). "Interestingly, while the PI3K and Akt inhibitors can only suppress the IR-induced EMT process and migration of breast cancer cells, knockdown Bmi-1 inhibits the behavior of breast cancer cells with or without IR." (PMID 25734775, 2015). "Our study supports the observations that Bmi1 could be a potential prognostic marker in breast cancer." (PMID 25348805, 2014). "The ERα-coupled Bmi1 regulatory pathway was subsequently evaluated with regard to its down-stream genes such as p16INK4a and cyclin D1 and clinic-pathological features in breast cancer." (PMID 24559156, 2014). "In this study, we at first identified a strong correlation of ERα status with Bmil expression in a collection of breast cancer tissues, and we then demonstrated the positive regulatory role ERα may play in transcriptional expression of the Bmi1 gene." (PMID 24559156, 2014). "Our data thus supports the observation that Bmi1 expression could serve as a prognostic marker in breast cancer." (PMID 25348805, 2014). "This study provides novel insights into various roles of Bmi1 in breast cancer and indicates that targeting Bmi1 could inhibit cancer stem cells and revert EMT." (PMID 25348805, 2014). "It has been suggested that in breast cancer the BMI-1 gene was present in the downstream signalling of the Hedgehog pathway and that activation of the same pathway determines an upregulation of the BMI-1 expression." (PMID 24821540, 2014). "The over-expression of Bmi1 and its 11-gene signature has been defined in breast carcinoma." (PMID 24559156, 2014). "Previous studies indicated that Bmi1 is overexpressed in various cancers including breast cancer." (PMID 25348805, 2014). "Over-expression of BMI-1 is one of the hallmarks of various cancer types, due to its relatively high amplification frequency and up-regulated expression of its mRNA and protein in a variety of tumors including bladder cancer, kidney cancer, and breast cancer." (PMID 25367080, 2014). "This may imply that the level of endogenous ERα more effectively affects the Bmi1 promoter than the concentration of cellular estrogen, which is consistent with the correlation found in the ERα status and the expression of Bmi1 in breast cancer." (PMID 24559156, 2014). "Immunostaining revealed strong correlation of Bmi1 and ERα expression status in breast cancer." (PMID 24559156, 2014). "Bmi1 mRNA was found to be higher in the plasma of breast cancer patients compared to normal sample." (PMID 25348805, 2014). "This demonstrates the important role which is played by ERα-coupled Bmi1 in human breast cancer." (PMID 24559156, 2014). "Increased expression of BMI-1 has been implicated in cancers, including colorectal, non-small cell pulmonary, hepatocellular, prostate, and breast cancer, medulloblastoma, multiple myeloma, and neuroblastoma." (PMID 23559850, 2013). "Additionally, robust evidence suggests that Bmi1 is critical to the invasive potential and contributes to tumorigenic capacity in colon cancer, medulloblastoma, laryngeal cancer, breast cancer, and prostate cancer." (PMID 23437065, 2013). "EMT promotes radioresistance in human tumor cells, down-regulation of Bmi-1 could be a novel strategy to sensitize radiotherapy by reversing EMT in human breast cancer." (PMID 22209830, 2012). "In our previous study, we showed that Bmi-1 could enhance the invasion and metastasis of human breast cancer and predicts poor survival, Bmi-1 silencing reverses the expression of EMT markers and inhibits the Akt/GSK3β/Snail pathway." (PMID 22209830, 2012).
breast carcinoma (continued). "Among these miRNAs, miR-200c was found to inhibit BMI1 polycomb ring finger oncogene (BMI1), a regulator of stem cell self-renewal, and led to inhibition of clonal expansion of breast cancer cells in vitro, and strongly suppressed the tumor formation driven by BCSCs in vivo." (PMID 24977105, 2012). "Taken together, these results indicate that Bmi-1 could be helpful to evaluate the prognosis in patients with breast cancer." (PMID 21276221, 2011). "Additionally, Bmi-1 has been verified as a predictor of prognosis in bladder cancer, prostate cancer, brain cancer, breast cancer, pancreatic cancer, and lung cancer." (PMID 20936121, 2011). "In addition, our data suggest that Bmi-1 has a critical effect on breast cancer tumorigenesis and lung metastasis." (PMID 21276221, 2011). "Because Bmi-1 expression was correlated with larger tumor size, lymph node involvement, distant metastasis and advanced clinical stage in breast cancer tissues, we hypothesized that Bmi-1 may regulate the progression of breast cancer." (PMID 21276221, 2011). "Furthermore, we also shed light on the biological impact of Bmi-1 on the invasive and metastatic properties of breast cancer cells." (PMID 21276221, 2011). "The expression pattern of Bmi-1, together with functional studies, indicate that Bmi-1 plays a prominent role in breast cancer progression and metastasis and opens the door for future studies addressing Bmi-1-targeted therapy in breast cancer." (PMID 21276221, 2011). "Thus, our findings indicate that Bmi-1 protein expression has a significant correlation with the prognosis of breast cancer." (PMID 21276221, 2011). "Mammosphere-derived breast cancer cells display self-renewal properties, overexpress stemness (Oct4 and BMI1) and cytoprotective markers (the IAP survivin protein) and telomerase activity, and are highly tumorigenic when injected at low concentrations in immunocompromized mice." (PMID 24212666, 2011). "We suggest that Bmi-1 contributes to the metastasis of breast cancer." (PMID 21276221, 2011). "In line with our study, up- regulation of BMI-1 has been shown to induce breast cancer metastasis." (PMID 21851624, 2011). "BMI-1 (B lymphoma mouse Moloney leukemia virus insertion region 1) is a self-renewal gene and overexpressed in multiple human cancers, including lung cancer, breast cancer, prostate cancer, ovarian cancer, and recently EC." (PMID 21851624, 2011). "Mouse xenograft studies indicate that coexpression of Bmi-1 and H-Ras in breast cancer cells can induce an aggressive and metastatic phenotype with an unusual occurrence of brain metastasis; although, Bmi-1 overexpression did not result in oncogenic transformation of MCF-10A cells." (PMID 21276221, 2011). "When comparing the transcription level of Bmi-1 in the different clinical groups, i.e. breast cancer, tissue taken in the vicinity of the tumor, fibroadenomas and breast tissue from non cancer controls, statistically significant differences were observed between the groups." (PMID 21162745, 2010). "Bmi-1 has been studied in plasma of breast cancer cells with healthy women as controls and results show that levels of Bmi-1 expression may be a surrogate marker of poor prognosis." (PMID 21162745, 2010). "Recent mouse xenograft studies using BMI1 and Ras co-overexpressing human mammary epithelial cells (HMECs) also support oncogenic roles for BMI1 in breast cancer development and metastasis of breast cancer cells." (PMID 20569464, 2010). "As the expression of Mel-18 and BMI1 inversely correlated in gastric cancer cell lines and gastric tumors, we suspected that similar to breast cancer cells, Mel-18 may negatively regulate the expression of BMI1 in gastric cancer cells." (PMID 20170541, 2010). "Furthermore, the Bmi-1 mRNA transcript levels are higher in plasma from breast carcinoma patients than in healthy controls, and this amplification of Bmi-1 is predictive of poor clinical outcome." (PMID 21637439, 2009).